APOE (apolipoprotein E)
Diseases named in the same sentence as APOE in open-access papers (continued):
Sharing a sentence is not in itself a finding about the gene and the disease.
gastric cancer (54 papers, 2007 to 2025). A primary or metastatic malignant neoplasm involving the stomach. "In gastric cancer, tumour‐associated macrophages (TAMs) contribute to tumour cell metastasis by secreting exosomes laden with APOE." (PMID 40437660, 2025). "Through integrated bioinformatics analysis and clinical cohort studies, this research found that the expression level of ApoE within gastric cancer tissues is upregulated and is associated with a shorter duration of overall survival." (PMID 40495209, 2025). "Experimentally, M2 macrophage-derived exosomes establish the base for gastric cancer cell migration through mediating the delivery of ApoE protein from tumor-associated macrophages to the tumor cells." (PMID 33728488, 2022). "Exosomes derived from tumor-associated macrophages promote the migration of gastric cancer cells via the transfer of functional apolipoprotein E." (PMID 31749791, 2019). "We therefore examined the association between APOE genotypes and T classification, N classification, and stage in gastric cancer patients." (PMID 26817942, 2016). "Our case-control study of 550 gastric cancer patients and 550 cancer-free controls evaluated for the first time the effects of APOE gene polymorphism and serum cholesterol levels on the risk of gastric cancer among a Chinese Han population." (PMID 26817942, 2016). "Future extension of these findings is necessary to clarify and further understand the association between APOE ε2 and gastric cancer risk in both ethnic populations." (PMID 26817942, 2016). "In contrast, a previous study reported a protective effect of the APOE ε2 allele against gastric cancer in an Italian Caucasian population." (PMID 26817942, 2016). "Intriguingly, the presence of the APOE ε2 allele is also associated with higher risk for both intestinal and diffuse types of gastric cancer." (PMID 26817942, 2016). "A potential association between APOE allele and the risk for gastric cancer has been implicated, but the specific allele involved and potential associations with the subtype and the grade of cancer malignancy need further clarification." (PMID 26817942, 2016). "Intriguingly, when examining the association between APOE ε2 and gastric cancer subtype, an increased risk of gastric cancer was noted in ε2 carriers for both intestinal gastric cancer (P = 0.017) and diffuse gastric cancer (P = 0.0006)." (PMID 26817942, 2016). "In gastric cancer, anaplastic thyroid carcinoma, and poorly differentiated endometrial adenocarcinoma, APOE overexpression was associated with advanced grade and stage or more aggressive low differentiated tumors." (PMID 25741405, 2015). "When results were stratified according to tumour histology, the significant association between apoE ε2 allele carriers and gastric cancer appeared to be limited to the intestinal type, with an OR of 0.31 (95% CI: 0.11 – 0.83)." (PMID 23098561, 2012). "One hundred and fifty-six gastric cancer cases and 444 hospital controls were genotyped for apoE polymorphism (ε2, ε3, ε4 alleles)." (PMID 23098561, 2012). "APSN+CXCL11+APOE+ fibroblasts were found to be associated with gastric cancer (GC) development." (PMID 39905493, 2025). "The APOE ε2 allele affects different lipid metabolism markers across various tumors, ApoA1 levels are significantly increased in patients with early-stage gastric cancer, whereas they remain relatively stable in those with advanced-stage gastric cancer." (PMID 39763652, 2024). "Interestingly, a recent report demonstrated that upregulation of JAK/STAT signaling pathway was associated with ApoE in gastric cancer." (PMID 30303984, 2018). "Since ε2 carriers have lower levels of serum total cholesterol than non-ε2 carriers, our findings suggested that the increased risk for gastric cancer by APOE ε2 allele might be mediated through lowered serum total cholesterol levels." (PMID 26817942, 2016).
gastric cancer (continued). "Since ε2 carriers have lower levels of serum total cholesterol than non-ε2 carriers, our findings suggest that the increased risk effect for gastric cancer by APOE ε2 allele might be mediated through lowered total cholesterol level." (PMID 26817942, 2016). "Since ε2 carriers have lower levels of serum total cholesterol than non-ε2 carriers, our findings suggest that the increased risk for gastric cancer by APOE ε2 allele might be mediated through lowered serum total cholesterol levels." (PMID 26817942, 2016). "Additionally, the association between APOE ε2 and increased risk of gastric cancer strengthened and became significant after adjustment for multiple testing (P = 0.0004)." (PMID 26817942, 2016). "Exosomes derived from M2 macrophages mediate intercellular transfer of PI3K-Akt signaling pathway activated by APOE in recipient gastric cancer cells, thereby reshaping the migration of cytoskeleton." (PMID 40963562, 2025). "The application of the antibodies of apoE has been reported to enhance the effect of anti-PD-1 antibody immunotherapy in the animal models of colorectal cancer, gastric cancer and HCC." (PMID 38976030, 2024). "We note that key nodes such as COL1A1, COL1A2, JUN, MMP9, APOE, and FOS displayed strongest strength of interactions in the network, suggesting that these genes are key genes associated with other proteins in gastric cancer." (PMID 39044041, 2024). "Among the prominent six genes highlighted in the protein-protein interaction network, higher expression levels of COL1A1, COL1A2, and APOE have also been confirmed to contribute to shorter survival in gastric cancer." (PMID 39044041, 2024). "For example, in gastric cancer, TAMs promote the migration of gastric cancer cells by transfer of functional Apolipoprotein E via sEVs to activate the PI3K-Akt signalling pathway." (PMID 37077181, 2023). "Previous study showed that APOE was highly expressed in gastric cancer, contributing to shorter survival." (PMID 36147474, 2022). "Mass spectrometric analyses of M2 macrophages-derived exosomes indicate apolipoprotein E (ApoE) on their surface and increase metastasis in gastric cancer cells after their fusion and transfer of ApoE to them." (PMID 35550636, 2022). "And overexpression of APOE significantly promoted the abilities of invasion and lymph node metastasis of gastric cancer cells." (PMID 35371313, 2022). "Many reports have shown that APOE can be overexpressed in human malignancies, including cancers of the bladder, breast, and ovary, colorectal cancer, renal cell carcinoma, and gastric cancer." (PMID 33521130, 2021). "Gastric cancer showed similar results; M2 macrophage-derived exosome-mediated apolipoprotein E (ApoE) transfer was found to increase the cancer cell migration in a PI3K/Akt signaling pathway activation-dependent manner." (PMID 34685596, 2021). "A recent study suggested that M2 macrophage-derived exosomes mediate an intercellular transfer of ApoE-activating PI3K-Akt signaling pathway in recipient gastric cancer cells to remodel the cytoskeleton-supporting migration." (PMID 34368234, 2021). "M2-Exos mediate intercellular transfer of the ApoE-activated PI3K-Akt signaling pathway within recipient gastric cancer cells thus it can remodel cytoskeleton-supporting migration." (PMID 34368234, 2021). "Studies have shown that APOE can not only promote the migration of gastric cancer cells by activating the PI3K-Akt signaling pathway but can also serve as a diagnostic marker for gastric cancer." (PMID 34195091, 2021). "For instance, TAMs can release the exosomes loaded with functional ApoE (Apolipoprotein E) to the cancer cells in tumor microenvironment and enhance the metastatic spread of gastric cancer cells." (PMID 32957534, 2020). "A study had shown that tumor-associated macrophages (TAMs) interacted with gastric cancer cells through APOE to promote the migration of gastric cancer cells." (PMID 33015179, 2020).
gastric cancer (continued). "Collectively, our findings signify that the exosome-mediated transfer of functional ApoE protein from TAMs to the tumor cells promotes the migration of gastric cancer cells." (PMID 29567987, 2018). "Mechanistically, M2 macrophage-derived exosomes mediate an intercellular transfer of ApoE-activating PI3K-Akt signaling pathway in recipient gastric cancer cells to remodel the cytoskeleton-supporting migration." (PMID 29567987, 2018). "Our results show that the presence of APOE ε2 allele and low serum levels of total cholesterol, HDL-cholesterol, apoA1 and apoA1/B ratio are associated with an increased risk of gastric cancer." (PMID 26817942, 2016). "Importantly, our study reports for the first time that APOE ε2 as a risk allele for both intestinal and diffuse types of gastric cancer in our studied population, which might be partly attributed to the lower serum total cholesterol of ε2 carriers compared to those with ε3 or ε4 alleles." (PMID 26817942, 2016). "In the study of differential gene expression between gastric cancer and the corresponding normal mucosa, apoE was found to be highly expressed in gastric cancer." (PMID 26817942, 2016). "One study evaluating the significance of APOE expression in gastric cancer, found that APOE mRNA was more highly expressed in gastric cancer tissue than corresponding normal mucosa." (PMID 25428203, 2014). "on the other hand suggested that APOE may be a key prognostic molecule with immunomodulatory function in gastric cancer and emphasized the importance of APOE in various cancer types including gastric cancer." (PMID 40292294, 2025). "Additionally, APOE has been reported to be overexpressed in several other malignancies, including bladder, breast and gastric cancer, and has been significantly correlated with tumour staging and LNM in pancreatic and endometrial cancer." (PMID 39810624, 2025). "ApoE expression in M2 macrophages regulates tumor migration in gastric cancer." (PMID 36639681, 2023). "Subgroup survival analysis of APOE mRNA in patients with gastric cancer." (PMID 38054821, 2023). "There was a strong link between ApoE levels and the risk of muscular invasion, making it a promising marker for predicting the invasions of gastric tumors, and overexpression of ApoE significantly promoted the abilities of invasion and lymph node metastasis of gastric cancer cells." (PMID 35892323, 2022). "ApoE was upregulated in gastric cancer, and such patients had shorter survival times." (PMID 35892323, 2022). "For instance, Apolipoprotein E protein in M2-Exos could encourage the dissemination of gastric cancer cells." (PMID 35328425, 2022). "In particular, APOE was closely related to muscular invasion, and may be a biomarker predicting muscular invasion of gastric cancer." (PMID 36147474, 2022). "Similarly, exosomes derived from M2 macrophages use apolipoprotein E (ApoE), a lipid-transporting lipoprotein found within the brain and periphery, to promote gastric cancer cell migration." (PMID 35910853, 2022). "In addition, TAMs-derived exosomes enriched apolipoprotein E (ApoE) promote the migration of gastric cancer cells by activation of PI3K/Akt/mTOR signaling pathway." (PMID 35250965, 2021). "Moreover, TAMs are uniquely immune cells population expressed ApoE in gastric cancer microenvironment." (PMID 29567987, 2018). "There was a trend toward an increased risk of gastric cancer for subjects with a copy of the APOE ε2 allele; however, this did not survive correction for multiple testing (P = 0.032)." (PMID 26817942, 2016). "We screened the APOE genotype in 550 gastric cancer patients and 550 non-cancer control individuals and found that the presence of the APOE ε2 and lower serum total cholesterol are associated with an increased risk for gastric cancer (all P ≤ 0.0005)." (PMID 26817942, 2016). "Higher apoE expression was found in gastric cancer, particularly in advanced T and N grades." (PMID 26817942, 2016).
gastric cancer (continued). "Immunohistochemistry showed that APOE was predominantly expressed in gastric cancer." (PMID 25428203, 2014). "Our case–control study of 156 gastric cancer cases and 444 hospital-based controls evaluated for the first time the effect of apoE genotypes and their interactions with selected demographic and lifestyle factors on the risk of gastric cancer among an Italian population." (PMID 23098561, 2012). "Therefore, the expression level of apoE may be a potential biomarker for predicting the malignancy of gastric cancer." (PMID 26817942, 2016). "M2 macrophage-derived exosomes mediate the intercellular transmission from M2 macrophages to gastric cancer (GC) cells, sustaining the connection between M2-exosomal ApoE, leading to the activation of the PI3K/Akt signaling pathway to remodel the cytoskeleton, and facilitating GC cells migration." (PMID 34722637, 2021). "Our results showed that the abnormal expression of FN1, TIMP1, SPP1, APOE, and VCAN influenced the prognosis of patients with gastric cancer." (PMID 33015179, 2020). "The results showed that FN1, TIMP1, SPP1, APOE, and VCAN were related to OS in gastric cancer patients (p < 0.01)." (PMID 33015179, 2020). "Furthermore, in gastric cancer, APOE+ TAMs facilitate tumor cell migration by transferring apolipoprotein E via exosomes, leading to cytoskeletal remodeling in cancer cells." (PMID 40835684, 2025). "ApoE is a specific and effective protein that mediates intercellular transfer in gastric cancer cells through M2 MDEs, activates the PI3K-Akt signaling pathway, and remodels the cytoskeleton to support and promote the migration of gastric cancer cells." (PMID 40612677, 2025). "Of note, exosomes derived from M2 macrophages of ApoE−/− mice did not affect the migration of gastric cancer cells." (PMID 34368234, 2021). "Data also showed that high expressions of fibronectin 1 (FN1), the tissue inhibitor of metalloproteinases 1 (TIMP1), secreted phosphoprotein 1 (SPP1), apolipoprotein E (APOE), and versican (VCAN) were related to a poor overall survival in gastric cancer patients." (PMID 33015179, 2020). "Furthermore, five of them (FN1, TIMP1, SPP1, APOE, and VCAN) were found to be related to gastric cancer." (PMID 33015179, 2020). "Mass spectrometric analysis reveals that M2-derived exosomes are rich in apolipoprotein E (ApoE), which can activate the PI3K-AKT pathway in tumor cells and induce the EMT and cytoskeleton rearrangement of gastric cancer cells, thus enhancing their metastatic potential as a consequence." (PMID 32161718, 2020). "However, APOE genotypes do not appear to influence the invasion and metastasis of gastric cancer as reflected by TN classification and stage." (PMID 26817942, 2016). "An inverse relationship between cholesterol levels and gastric cancer (GC) has been previously reported, although the relationship between apoE genotypes and GC has not been explored so far." (PMID 23098561, 2012).
melanoma (53 papers, 2013 to 2025). A malignant, usually aggressive tumor composed of atypical, neoplastic melanocytes. "Consistent with this theory, APOE ε4 carriers perform better on cognitive tasks, have a lower risk of proximal colorectal cancer, and increased survival from melanoma." (PMID 40356022, 2025). "People with melanoma who are carriers of the APOE ε4 allele have higher survival rates than those with APOE ε2." (PMID 40149482, 2025). "Tumor secreted apoE appears to be a potent immune cell checkpoint and targeting apoE is associated with enhanced tumor immunity in the mouse melanoma model." (PMID 36341364, 2022). "The known association of apoE with immunosuppression and its conflicting observations described in tumor biology led us to examine the role of apoE in an immune resistant mouse melanoma model." (PMID 36341364, 2022). "It has been previously reported that patients with the ApoE ε4 allele showed a lower chance of melanoma progression and metastasis compared to patients with the ApoE ε2 allele." (PMID 35892323, 2022). "We evaluated the presence of multiple genes associated with immunosuppression in the B16-F10 melanoma cell line, ApoE was the most highly expressed immune-suppressive transcript in the cell line." (PMID 36341364, 2022). "Melanoma patients’ apoE subtypes are found strongly associated with disease progression and efficacy of immunotherapy, which is considered as the first-time demonstration that pre-existing genes in the genome can influence malignant progression and patients’ response to immunotherapy." (PMID 38976030, 2024). "ApoE attenuates inflammation by complex formation with activated C1q, while most recently it was shown that common germline variants of the human APOE gene modulate melanoma progression and survival." (PMID 36341364, 2022). "Recently, APOE variants were found to be involved in melanoma progression and survival." (PMID 32749065, 2020). "On the other hand, expression of some APOE variants, like APOE4, is associated with an improved responsiveness of melanoma patients to anti-PD1 ICT, suggesting that both APOE and TREM-2 expressions on myeloid cells can be used to stratify patients who might benefit from this therapeutic strategy." (PMID 36161514, 2023). "Interestingly, synthetic LXR agonists such as GW inhibit primary melanoma progression by activating stromal LXRβ and causing ApoE secretion (a melanoma-extrinsic event), whereas their effects on metastasis are mediated through ApoE secretion in both the tumoral and stromal compartments." (PMID 29199269, 2017). "Previous studies have shown that pharmacological activation of ubiquitously expressed LXRβ significantly upregulates APOE expression and suppresses melanoma tumor progression." (PMID 40664892, 2025). "Studies have shown that overexpressing certain microRNAs that silence ApoE in metastatic melanoma cells promotes metastasis formation." (PMID 40662483, 2025). "A similar role of APOE expression has been identified in the metastases of melanoma cells and non‐small cell lung cancer." (PMID 39810624, 2025). "In stark contrast to tumour‐derived ApoE, which often gets repressed as melanoma progresses, the expression of stroma‐derived ApoE expression is significantly influenced by host genetic factors." (PMID 40662483, 2025). "Growing evidence indicates that both tumour‐derived and stroma‐derived ApoE play a significant role in the battle against melanoma." (PMID 40662483, 2025). "APOE reportedly functions as a metastasis‐suppressive protein by inhibiting both the invasiveness of melanoma cells and the recruitment of endothelial cells, thus serving as a barrier to metastatic colonization." (PMID 39810624, 2025). "DNAJA4 and ApoE are essential for suppressing metastasis, and through its interaction with melanoma cell LRP1 and endothelial cell LRP8 receptors, cancer-secreted ApoE reduces invasion and metastatic endothelial recruitment (MER)." (PMID 39199614, 2024).